HLA-E (major histocompatibility complex, class I, E)
Diseases named in the same sentence as HLA-E in open-access papers (continued):
Sharing a sentence is not in itself a finding about the gene and the disease.
melanoma (37 papers, 2011 to 2025). A malignant, usually aggressive tumor composed of atypical, neoplastic melanocytes. "Patients with melanoma, glioblastoma, gastric cancer, breast cancer, and ovarian cancer were reported to have high expression of HLA-E and the expression level of HLA-E was linked to clinical outcomes." (PMID 40066089, 2025). "Given that NK cells are known potent producers of IFN-γ, it is likely that the presence of NK cells could cause an upregulation of HLA-E on melanoma cells." (PMID 33802954, 2021). "The expression of HLA-E is increased in multiple human cancers including lung, pancreas, stomach, colon, head and neck, melanoma, and prostate cancers." (PMID 39706891, 2025). "Further studies have also argued that HLA-E is widely expressed in human tumors and, additionally, high HLA-E expression seems to correlate with good prognosis in melanoma and glioblastoma." (PMID 36829496, 2023). "HLA-E is typically expressed at negligible levels in melanoma cells, but surface expression of HLA-E can become drastically upregulated in the presence of IFNγ, which is produced in high quantities by NK cells." (PMID 38067178, 2023). "A study was conducted to investigate the relationship between HLA-E molecules and melanoma, revealing elevated levels of soluble HLA-E molecules in stage IV melanoma patients." (PMID 38057843, 2023). "For example radiation increases HLA-E surface expression in glioblastoma and also Qa-1b expression in murine models of melanoma and colorectal cancer." (PMID 36560403, 2022). "Ionising radiation downregulated surface HLA-E expression on melanoma cells, however the effect of radiation on HLA-E expression appears to be dependent on tumour type and the model investigated." (PMID 36560403, 2022). "It has been established that IFN-gamma significantly increased the surface expression of HLA-E and the shedding of soluble HLA-E by melanoma tumor cells." (PMID 35323192, 2022). "It has also been shown that melanoma cells have higher HLA-E expression levels than healthy melanocytes, and that this expression leads to protection from lysis by NK cells, as was confirmed by NKG2A blocking experiments." (PMID 34572949, 2021). "In the context of TME-mediated immune escape strategies, HLA-E expression is often elevated in melanoma." (PMID 33925968, 2021). "HLA-E is expressed on many tumors, including melanoma, and high levels of soluble HLA-E are found in melanoma." (PMID 33827575, 2021). "Together with HLA-G1 expression decrease, the HLA-E level was downregulated in FON melanoma cells exposed to 10 and 20 Gy, mainly due to an indirect influence of HLA-G1 decrease induced by IR concerning the HLA-E stabilizing ability of HLA-G1 molecule." (PMID 32612950, 2020). "Studies on human endothelial cells and other melanomas report that HLA-E can be shed upon treatment with IFN-γ, IL-1β or TNF-α." (PMID 24236107, 2013). "We previously reported a positive correlation between the presence of seric HLA-E molecules and melanoma." (PMID 24204708, 2013). "We have previously shown that IFN-γ increased the surface expression of HLA-E and the shedding of soluble HLA-E by melanoma cells." (PMID 21712991, 2011). "We also reported that melanoma cell lines can produce soluble forms of HLA-E (sHLA-E) in vitro, by protease dependant shedding of surface molecules, and that this production was increased by IFN-γ." (PMID 21712991, 2011). "Our results better agree with two cDNA profiling studies of advanced melanoma in which high levels of HLA-E transcripts contributed molecular signatures of favourable prognosis, and a recent study on glioblastoma." (PMID 22032294, 2011). "We previously observed, in collaboration with pathologists, a frequent expression of HLA-E by melanomas and colon carcinomas." (PMID 21712991, 2011).
melanoma (continued). "On that basis we selected MSR3‐mel, a melanoma‐derived cell line reported to display an epigenetic silencing of HLA‐I genes by hypermethylation, also preventing the presence of HLA‐I leader sequences binding to HLA‐E." (PMID 40347012, 2025). "HLA-E is highly expressed in various tumors, including melanoma, colon cancer, and glioblastoma." (PMID 39192888, 2024). "Melanoma patients’ sera contain IgG antibodies against HLA-E as well as HLA-B and HLA-C." (PMID 35323192, 2022). "HLA-E is a major histocompatibility complex gene, and is expressed in many types of cancers and served as a potential prognosticator of some cancers such as melanoma and colorectal cancer." (PMID 35675043, 2022). "However, the potential role of HLA-E as antigen-presenting molecule for tumor-specific CD8+ T cells should be investigated because of the frequent overexpression of HLA-E in some cancers such as melanoma, colorectal carcinoma and cervical adenocarcinoma." (PMID 34446788, 2021). "Furthermore, HLA-E and HLA-G expression levels are often elevated in the course of typical melanoma immune escape strategies." (PMID 33925968, 2021). "We found abundant HLA-E expression in all melanoma cell lines that were used in this study." (PMID 33925968, 2021). "Furthermore, a cell line based study suggested that the upregulation of HLA-E represents a mechanism of tumor escape from NK cytotoxicity in ovarian cancer and melanoma." (PMID 34834481, 2021). "Moreover, HLA-E is expressed by tumour cells of the following cancers: colorectal, laryngeal, ovarian, breast, melanoma, lymphoma and glioma." (PMID 24093459, 2013). "While previous reports supporting a role for MMPs in the shedding of HLA-E from melanoma cells encouraged us to focus on a possible role for MMPs in this study, the participation of other mechanisms and JEV proteins in this shedding process has not been investigated." (PMID 24236107, 2013). "In conclusion, the current study provides for the first time evidence of an elevated sHLA-E in sera from melanoma patients, indicating that HLA-E might serve as a clinical marker for the prognosis or prediction of the clinical outcomes of these cancers especially in the context of immunotherapy." (PMID 21712991, 2011). "MDA-MB-231 cells express many of these ligands, and they were present in purified MDA-MB-231 (breast cancer), Gli36 (glioblastoma) and B16-F1 (melanoma) blebbisomes, including PD-L1, PD-L2, B7-H3, VISTA, PVR and HLA-E." (PMID 39984653, 2025). "Although HLA-E is either absent or just weakly expressed in melanoma, the presence of NK cells followed by a high Interferon-gamma response is likely what increases HLA-E in melanoma cells." (PMID 38057843, 2023). "HLA-E and HLA-E HCs are more prevalent on tumor cells, including melanoma, as evidenced by immunostaining with the monospecific mAbs TFL-033 and the polyreactive mAb MEM-E/02, which bind to the cryptic epitopes exposed on the heavy chain of HLA-E." (PMID 35323192, 2022). "The immune modulatory functions of HLA-E were determined in the stable transfected HLA-E overexpressing (HLA-G negative) melanoma cell line BUF1088." (PMID 27589686, 2016). "Here, we found a trend towards increased concentrations of soluble HLA-E molecules in the sera of stage IV melanoma patients (data not shown)." (PMID 24204708, 2013). "Since sHLA-E release by melanoma cells is mainly matrix metalloproteinase-dependant, TNF-α effect on HLA-E production could be due to the ability of TNF-α to promote matrix metalloproteinase expression." (PMID 21712991, 2011). "Generally, HLA-E is absent or expressed in low amounts by melanomas." (PMID 33802954, 2021). "IFN-γ also upregulated Qa-1 and HLA-E on murine and human tumour cells, respectively, and blocking NKG2A converted cancer vaccines into effective therapies in four different solid tumour models (TC-1 lung epithelial tumour, B16F10 melanoma, RMA T cell lymphoma, and MC38 colon carcinoma)." (PMID 30626155, 2019).
melanoma (continued). "We previously reported that melanoma cells produce, in vitro, soluble forms of the non-classical MHC class I molecule HLA-E (sHLA-E)." (PMID 21712991, 2011).
COVID-19 (34 papers, 2020 to 2025). A disease caused by infection with severe acute respiratory syndrome coronavirus 2. "The intricate relationship between HLA-E polymorphisms and NK cell responses was explored, providing insights into the observed anergic state in severe COVID-19 patients." (PMID 40391199, 2025). "Considering the pivotal role of HLA-E as a major modulator of NK cell function and its depletion in the pathogenesis of COVID-19, this investigation identifies an association between HLA-E polymorphism and susceptibility to SARS-CoV-2." (PMID 40391199, 2025). "We did not observe any association between serum sHLA-E levels and patients’ HLA-E genotype or COVID-19 severity." (PMID 41153412, 2025). "It was shown that NK cells expressing NKG2A were activated in patients with COVID-19 due to the interactions of the NKG2A receptors with the HLA-E molecules, presenting a SARS-CoV-2 Nsp13-encoded peptide." (PMID 36768315, 2023). "The deletions of KLRC2 and, at a lower degree, the HLA-E* 0101 allele are independent risk factors for severe COVID-19, suggesting that genetic variants in the NKG2C/HLA-E axis have a significant impact on COVID-19 severity." (PMID 35625739, 2022). "The deletion of KLRC2 and HLA-E*0101/0103 allelic variants were evaluated in a study cohort of 361 patients, of which 92 had mild COVID symptoms, and 269 patients had severe COVID-19." (PMID 35062298, 2022). "Non-classical HLA class I molecules with tolerogenic activity, such as HLA-G and HLA-E, have also been associated with COVID-19." (PMID 35062298, 2022). "Moreover, the study delved into the immunomodulatory function of HLA-G and its interaction with HLA-E, revealing significant associations with COVID-19 severity." (PMID 40391199, 2025). "HLA-E*01:01 allele and heterozygous HLA-E*01:01/03 genotype are associated with severe COVID-19, which may account for the individual difference in NK cell responses following SARS-CoV-2 infection." (PMID 39450171, 2024). "Consistently, genetic variants of the NKG2C/HLA-E axis and in particular the presence of the HLA-E*0101 allele have been previously reported to have a significant impact on the development of severe forms of COVID-19." (PMID 37342247, 2023). "Furthermore, an Austrian study showed that the heterozygous HLA-E*0101/0103 variant and the HLA-E*0101 allele was associated more severe COVID-19." (PMID 34223911, 2021). "In conclusion, our study confirms previous observations regarding the impact of NKG2C and HLA-E genetic variability on the risk for SARS-CoV-2 infection, the development of COVID-19, and the severity of its symptoms." (PMID 41153412, 2025). "We observed that genes encoding HLA class 1 (HLA-E, PSMA-6, TAP1, IFI30) were enriched in COVID-19 ECs." (PMID 37029220, 2023). "Authors identified upregulated HLA-E in bronchoalveolar lavage (BAL) fluid of COVID-19 patients, and suggested, therefore, a receptor-ligand-driven expansion of adaptive NK cells." (PMID 36899273, 2023). "The abolition of NKG2A+ NK cell inhibition by the viral peptide SARS-CoV-2-Nsp13 in patients with COVID-19 leads to their activation through the HLA-E." (PMID 37240393, 2023). "It should be also noted that the SARS-CoV-2 Spike protein is supposed to be involved in the overexpression of the HLA-E molecule in the immune and stromal cells in the bronchoalveolar lavage fluids of COVID-19 patients." (PMID 36768315, 2023). "One of those studies showed that both HLA-E*01:01 and NKG2C del variants are more frequently present in hospitalized Austrian COVID-19 patients, and both genotypes are independent risk factors for severe COVID-19." (PMID 36899273, 2023). "It has been proposed to use HLA-E restricted CD8+ T cells to treat severe COVID-19 patients in the early stage of SARS-CoV-2 infection." (PMID 38257752, 2023). "The HLA-E molecule has been suggested to be highly expressed in infected cells from COVID-19 patients." (PMID 35062298, 2022).
COVID-19 (continued). "Herein, we describe the association of HLA-A, B, C, DRB1, DRB345, DQA1, DQB1, DPA1, DPB1, and HLA-E, F, G, and H on the results of molecular detection of COVID-19, or, in some cases, on antibody detection upon first testing." (PMID 36671730, 2022). "and (d) Given HLA-E-CD94/NKG2A axis plays critical roles in COVID-19 and HLA-E cell surface expression depends other leader sequence peptides, particularly derived from HLA-G, what is the relationship between HLA-G and HLA-E expression?" (PMID 34938296, 2021). "Similar proportion of homozygosis for HLA-E*0101 (27.9%) and HLA-E*0103 (26.2%) was found in patients with mild COVID-19, whereas HLA-E*0101 homozygosis (47.4%) was 2.3- fold more frequent than HLA-E*0103 homozygosis (21.5%) in patients with severe COVID-19." (PMID 34122423, 2021). "By contrast, the expression of NKG2C, an activating receptor of HLA-E implicated in the control of CMV infections, remained unmodified in COVID-19 patients." (PMID 32612152, 2020). "In patients with severe to moderate COVID-19, HLA-E is upregulated in the lung epithelium." (PMID 41440003, 2025). "Additionally, the S1 peptide exhibits higher affinity for HLA-E∗01:01 than HLA-E∗01:03, supporting the role of the HLA-E/S1 peptide complex in generating NK cell anergy and exacerbating the severity of COVID-19." (PMID 40391199, 2025). "Unsurprisingly, the “near to epithelial cell” myeloid population shows higher COVID-19 signatures score and highly expresses multiple MHC Class I and II related genes, such as B2M, HLA-A, HLA-B, HLA-C, HLA-E, and HLA-DRA, which are associated with the interferon (IFN) response." (PMID 37120608, 2023). "Antibody mediated blockade of NKG2A has been proposed as a novel COVID-19 treatment and therefore selinexor mediated downregulation of HLA-E may also potentially participate in the anti-viral efficacy of selinexor." (PMID 34926302, 2021). "Besides, the same percentage of HLA-E*0101 and *0103 homozygosis (19.4%) was found in patients with critical COVID-19, in which HLA-E*0101-0103 heterozygosis was predominant (61.1%) (p<0.01)." (PMID 34122423, 2021). "Therefore, HLA-E heterozygosis was 1.3- and 1.9-fold more present in patients with critical COVID-19 regarding patients with mild and severe COVID-19, respectively." (PMID 34122423, 2021). "Results obtained within this study indicate that the presence of deletion within the NKG2C/KLRC2 gene, as well as NKG2A rs7301582, HLA-E rs1264457, MICB rs065075, and MICA rs1051792 SNPs, could be associated with COVID-19 susceptibility and the severity of the disease." (PMID 41153412, 2025). "The concomitantly increased KIR molecule density observed here contributes to a widely increased HLA class I and HLA-E-mediated inhibitory control on NK cell activation signaling and is in line with previous reports suggesting that NK cells are in a dysfunctional state in COVID-19 patients." (PMID 33861802, 2021). "Besides, patients with critical COVID-19 showed higher predominance of HLA-E heterozygosis, which may be related to a more permissive peptide repertoire presentation that is nevertheless not translated to a better cytotoxic response." (PMID 34122423, 2021). "The interaction between HLA-E and NKG2A provides a partial explanation for the noted anergic condition observed in severe COVID-19 patients, ultimately resulting in the depletion of NK cells." (PMID 40391199, 2025). "This study aims to investigate the potential impact of HLA-E, HLA-G, and KIR genotypes on the severity of COVID-19, providing insights into the role of genetic determinants in immune response, disease progression, and individual susceptibility." (PMID 40391199, 2025). "The KLRC2 protein (also: NKG2C) can bind to CD94 and HLA-E to form a functional complex, and thus, the depletion of KLRC2 is likely to have a significant impact on the development of severe COVID-19." (PMID 37403156, 2023).
COVID-19 (continued). "Mechanistically, SARS-CoV-2 can induce NK cell exhaustion via Spike 1 protein binding to the HLA-E of lung epithelial cells, thereby triggering the HLA-E/NKG2A pathway, suggesting the important role of NK cells in pathological COVID-19 processes." (PMID 35911747, 2022). "Consistent with this, HLA-E, a major ligand for NKG2C-expressing adaptive NK cells, is upregulated in BAL fluid of COVID-19 patients." (PMID 34192268, 2020). "We found that NK cells isolated from the blood of ARDS COVID-19 patients retained cytotoxic functions, and that incubation with monalizumab, an anti-NKG2A mAb blocking the inhibitory interaction with HLA-E, was able to unleash their killing ability." (PMID 32612152, 2020). "Here, we found up-regulated HLA-E in immune and stromal cells in BAL fluid of COVID-19 patients, suggesting a receptor-ligand driven expansion of adaptive NK cells." (PMID 32826343, 2020). "In addition to the HLA-B -> HLA-E -> NKG2A axis, COVID-19 severity appears to be influenced by genetic variation in other NK cell receptors." (PMID 39487235, 2025). "Patients with COVID-19 showed downregulation of genes involved in the AP-1 transcription factor pathway (including JUN, JUNB, JUND, and FOSB) as well as HLA genes (including HLA-E, HLA-DRB1, HLA-DRA, and HLA-DPB1)." (PMID 36992700, 2023). "In theory, HLA-E-restricted CD8+ T cells against SARS-CoV-2 can be affordable and easily developed with donations of COVID-19 convalescent allogeneic samples in large quantities, collected and used when needed for serious COVID-19 cases." (PMID 37533516, 2022). "This receptor may have a similar role in COVID-19 patients who frequently present with abnormally high levels of IL-621,46–48, which drives the expression of the NKG2A ligand HLA-E on T cells, B cells, and macrophages." (PMID 33972535, 2021).